OTUD6A (OTU deubiquitinase 6A)
Diseases named in the same sentence as OTUD6A in open-access papers:
OTUD6A is named in the same sentence as 29 diseases in open-access papers, as found by Europe PMC text mining. Sharing a sentence is not in itself a finding about the gene and the disease. The quoted sentences say what the papers report.
colorectal cancer (5 papers, 2020 to 2025). A primary or metastatic malignant neoplasm that affects the colon or rectum. "In the context of human colorectal cancer, low expression of OTUD6A leads to suppressed mitochondrial fission and reduced cell growth of proliferating cells." (PMID 40328871, 2025). "OTUD6A was previously reported to be an oncogene in colorectal cancer (CRC), PCa and BC, and OTUD6A is overexpressed in CRC, PCa and BC tissues." (PMID 38685067, 2024). "Here, we investigate OTUD6A is a novel upstream of Drp1 and upregulated in patients with colorectal cancer, which suggested a potential mechanism linking OTUD6A to mitochondrial fission in cancer." (PMID 33070427, 2020). "To uncover the potential function of OTUD6A in cancer, we firstly performed IHC analysis to assess the OTUD6A protein levels in cancer tissues and found that OTUD6A was aberrantly upregulated in colorectal cancer tissues compared with normal tissues." (PMID 33070427, 2020). "OTUD6A is upregulated in human patients with colorectal cancer." (PMID 33070427, 2020). "However, it has been demonstrated that OTUD6A enhances the protein levels of one of the crucial EMT inducers, Snail, and promotes colorectal cancer by deubiquitinating and stabilizing DRP1." (PMID 33669244, 2021).
colitis (3 papers, 2024 to 2025). Inflammation of the colon. "In vivo, OTUD6A deficiency was observed to result in reduced severity of colitis induced by DSS or TNBS, as well as CAC induced by AOM/DSS." (PMID 38892354, 2024). "Additionally, bone marrow transplantation experiments demonstrated that the exacerbation of DSS-induced colitis was caused by OTUD6A in myeloid cells." (PMID 38892354, 2024). "The deubiquitinase OTUD6A in macrophages exacerbates intestinal inflammation and colitis by activating the NLRP3 inflammasome." (PMID 39809743, 2025). "In an in vitro cellular model of dextran sulfate sodium (DSS)-induced colitis, the DUB OTU domain-containing protein 6A (OTUD6A) interacted with structural domains of the NLRP3 inflammasomes inducing their deubiquitination." (PMID 38193803, 2024).
prostate carcinoma (3 papers, 2022 to 2025). A carcinoma that arises from epithelial cells of the prostate gland. "OTUD6A promotes the proliferation of prostate cancer cells by deubiquitinating and stabilizing the Brg1 and AR proteins." (PMID 41050073, 2025). "We also found that compared to prostate cancer patients with two normal copies of OTUD6A, those with OTUD6A amplification showed higher OTUD6A mRNA expression (P = 0.0285)." (PMID 35233061, 2022). "OTUD6A, a deubiquitinase, is amplified in prostate cancer and correlates with poor survivability, increasing the growth of prostate cancer cell lines and PDX models." (PMID 35233061, 2022). "To investigate OTUD6A function in prostate cancer, we depleted OTUD6A in the PCa cell lines LNCaP, C4-2, VCaP and PC-3 by using two different shRNA constructs." (PMID 35233061, 2022). "Both the Brg1 and AR proteins are pro-oncogenes in prostate cancer, and thus, OTUD6A could promote the proliferation of prostate cancer cells by deubiquitinating and stabilizing the brahma-related gene 1 (Brg1) and androgen receptor (AR) proteins." (PMID 41050073, 2025). "Mechanistically, PDIK1L may stabilize oncogenic signaling by modulating DNA repair or metabolic adaptations, akin to OTUD6A, a deubiquitinase recently shown to stabilize c-Myc and promote metabolic remodeling in prostate cancer." (PMID 41262299, 2025). "In our study, we found that OTUD6A was upregulated in Pten-depleted prostate cancer tissues; and that OTUD6A could deubiquitinate and stabilize the Brg1 protein." (PMID 35233061, 2022). "Furthermore, the interaction of OTUD6A with Brg1 and AR was also verified in other prostate cancer cell lines, including PC-3, LNCaP, and C4-2 cells, through IP-IB analysis." (PMID 35233061, 2022). "Intriguingly, we found that unlike OTUD6B, OTUD6A was specifically and highly amplified in prostate cancer." (PMID 35233061, 2022).
bladder cancer (2 papers, 2024 to 2026). "Furthermore, OTUD6A protein level has a positive correlation with CDC6 protein level, and high protein levels of OTUD6A and CDC6 are associated with poor prognosis in patients with bladder cancer." (PMID 38685067, 2024). "To test this possibility, we first examined endogenous OTUD6A expression in the immortalized human uroepithelial cell line SV-HUC-1 and five bladder cancer (BCa) cell lines." (PMID 38685067, 2024).
breast carcinoma (2 papers, 2025). "The study revealed that in breast cancer, OTUD6A stabilized DNA topoisomerase 2 binding protein 1 (TopBP1) by inhibiting its K48-Ub." (PMID 40469292, 2025). "In breast cancer, OTUD6A increases the stability of TopBP1 by cleaving the K48-type polyUb chain, thereby initiating the DDR pathway, leading to tumor cell proliferation, migration, and invasion." (PMID 41050073, 2025). "OTUD6A cleaves the K48-type polyUb chain of nucleolin and the K63-type polyUb chain of caspase 7, which enhanced the cell cycle progression and induced cell proliferation in breast cancer MCF7 cells." (PMID 41050073, 2025). "It promoted its stabilization, while OTUD6A also cleaved the K63-type polyUb chain of caspase 7, an apoptotic caspase, and promoted its degradation, which enhanced the cell cycle progression and induced cell proliferation in breast cancer MCF7 cells." (PMID 41050073, 2025). "In breast cancer (BC), OTUD5, YOD1, OTUD6A, OTUD7B, ZRANB1, and TNFAIP3 were characterized as carcinogenic drivers." (PMID 40469292, 2025). "Furthermore, OTUB1 and OTUD6A deubiquitinated and stabilized CHK1 and TopBP1, which regulated DNA damage and repair and promoted radiation resistance in lung and breast cancer, respectively." (PMID 40469292, 2025).
asthma (1 paper, 2026). "Furthermore, adeno-associated virus 6-mediated OTUD6A silencing in murine lungs markedly ameliorates asthma phenotypes." (PMID 41560298, 2026). "The study finds a significantly upregulation of OTUD6A in asthma patients and murine lungs, with predominant localization in airway epithelial cells." (PMID 41560298, 2026).
chronic asthma (1 paper, 2026). An asthma that is characterized by the development of persistent airway inflammation and recurrent attacks of breathlessness and wheezing, which vary in severity and frequency. "Genetic ablation of Otud6a prevents house dust mite (HDM)-induced AHR, airway inflammation, mucin hypersecretion in both chronic and acute asthma models, as well as airway remodeling in chronic asthma model." (PMID 41560298, 2026).
clear cell renal carcinoma (1 paper, 2024). A malignant epithelial neoplasm of the kidney characterized by the presence of lipid-containing clear cells within a vascular network. "We then established stable OTUD6A knockdown cancer cell lines including T24, 5637, 786-O (clear cell renal carcinoma), KYSE150 (oesophageal squamous carcinoma) and H1299 (non-small cell lung cancer)." (PMID 38685067, 2024).
colorectal tumor (1 paper, 2020). "The demonstration of OTUD6A and Drp1 expression in colorectal tumor and the interaction between the two proteins support our hypothesis that OTUD6A might play a promotive role in cancer progression." (PMID 33070427, 2020).
Meier-Gorlin syndrome (1 paper, 2024). "Importantly, similar to Meier-Gorlin syndrome in humans, which can be caused by CDC6 mutation, depletion of OTUD6A in mice causes postnatal growth retardation, suggesting that OTUD6A is required for normal development at least partially through maintenance of CDC6 protein stability." (PMID 38685067, 2024).
ovarian carcinoma (1 paper, 2020). A malignant neoplasm originating from the surface ovarian epithelium. "Therefore, according to the results presented here, it is possible that OTUD6A also has an oncogenic role in ovarian cancer via regulating Drp1." (PMID 33070427, 2020).
Ovarian tumor (1 paper, 2021). "OTUD6A (OTU domain-containing protein 6A) is a member of Ovarian tumor-associated proteases (OTUs) comprising sixteen DUB members." (PMID 33669244, 2021).
prostate tumors (1 paper, 2022). "We found that compared to that in adjacent normal tissues, the OTUD6A protein level in prostate tumor tissues was remarkably elevated." (PMID 35233061, 2022). "Further clinical investigation showed that the OTUD6A protein was highly expressed in prostate tumors, and increased OTUD6A expression correlated with a higher biochemical recurrence risk after prostatectomy." (PMID 35233061, 2022).
renal carcinoma (1 paper, 2024). A carcinoma arising from the epithelium of the renal parenchyma or the renal pelvis. "The protein levels of OTUD6A and CDC6 were also consistent in renal carcinoma tissues." (PMID 38685067, 2024). "Moreover, both the OTUD6A and CDC6 protein levels are increased in BCa and renal carcinoma tumour tissues, and the trend in OTUD6A protein level is consistent with the trend in CDC6 protein level in both BCa and renal carcinoma tissues." (PMID 38685067, 2024).
tumor (6 papers, 2020 to 2026). "Consistent with the observation from in vitro experiments, overexpression of CDC6 rescued the increased chemosensitivity caused by OTUD6A knockdown in gemcitabine-treated T24 tumours." (PMID 38685067, 2024). "To explore the function of OTUD6A in vivo, we implanted OTUD6A intact or depleted C4-2 cells into NOD/SCID mice and observed that OTUD6A depletion dramatically attenuated tumor growth in these immune deficient mice." (PMID 35233061, 2022). "Collectively, these findings demonstrate that PRDM1 acts as a tumor suppressor in BCa by inhibiting OTUD6A transcription and promoting CDC6 degradation." (PMID 41724787, 2026). "The study identifies ovarian tumor deubiquitinase 6A (OTUD6A), a deubiquitinase with established oncogenic roles, as a novel regulator of airway inflammation and remodeling." (PMID 41560298, 2026). "PLK1 and Cyclin-dependent kinases regulatory subunit 2 (CKS2) can drive mitosis and cell cycle progression in tumor cells through deubiquitination, suggesting that OTUD6A is a potential therapeutic target for cancer." (PMID 41050073, 2025). "CKO mice are less prone to BCa tumorigenesis induced by BBN, and knockdown of OTUD6A inhibits tumour progression in vivo." (PMID 38685067, 2024). "Patients bearing BCa tumours with relatively high levels of OTUD6A or CDC6 showed poorer overall survival (OS) outcomes." (PMID 38685067, 2024). "Taken together, these data demonstrated that OTUD6A promotes CDC6-ATR-Chk1 signalling pathway activity to confer chemoresistance on tumour cells." (PMID 38685067, 2024). "Consistent with the in vitro results, enhanced chemosensitivity to gemcitabine and increased DNA damage induced by gemcitabine were observed in OTUD6A-knockdown T24 tumours." (PMID 38685067, 2024). "We further characterized the pivotal role of OTUD6A in tumour progression and chemoresistance via upregulation of CDC6." (PMID 38685067, 2024). "The clinical data also showed that the Brg1 protein level was highly correlated with OTUD6A expression as well as tumor progression in PCa." (PMID 35233061, 2022). "Our results implicate a potential role for OTUD6A dysregulation in mitochondrial dynamics and in tumor cell growth." (PMID 33070427, 2020). "Here, we show a straightforward mechanism for how OTUD6A impacts mitochondrial morphology, leading to tumor cell growth." (PMID 33070427, 2020). "Moreover, ectopic expression of CDC6 effectively reversed the OTUD6A knockdown-mediated tumour growth inhibition in vivo." (PMID 38685067, 2024). "Knockdown of OTUD6A in T24 and 786-O cells significantly inhibited tumour growth." (PMID 38685067, 2024). "Based on the results presented above, OTUD6A might function as a tumor oncogene through its action toward mitochondrial fission." (PMID 33070427, 2020). "Therefore, targeting AR and Brg1 could largely reduce tumor cell growth in OTUD6A-overexpressing PCa cells." (PMID 35233061, 2022). "Depletion of OTUD6A inhibits CDC6 expression as well as BBN-induced BCa tumorigenesis and tumour progression." (PMID 38685067, 2024). "In addition, OTUD6A inhibits TopBP1 ubiquitination by disrupting the interaction between TopBP1 and UBR5 and promotes tumour cell resistance to chemoradiotherapy." (PMID 38685067, 2024). "Moreover, high expression of OTUD6A was strongly correlated with increased prostate-specific antigen (PSA) levels, high Gleason scores, and elevated tumor stages of PCa patients." (PMID 35233061, 2022). "Moreover, the protein but not the mRNA level of CDC6 was decreased in OTUD6A-knockdown T24 tumours." (PMID 38685067, 2024).
cancer (5 papers, 2020 to 2025). A tumor composed of atypical neoplastic, often pleomorphic cells that invade other tissues. "Knockdown of OTUD6A caused hypersensitivity to gemcitabine and methotrexate in different cancer cell lines detected." (PMID 38685067, 2024). "From qPCR screening, we identified and validated that the cancer gene CKS2 encoding Cyclin-dependent kinases regulatory subunit 2 is the most upregulated cell cycle regulator when OTUD6A is overexpressed." (PMID 33669244, 2021). "Collectively, these results indicated that OTUD6A promotes the tumorigenicity of human cancer cells by upregulating CDC6." (PMID 38685067, 2024). "Similar to the observations in OTUD6A knockdown and overexpressed cancer cells, knockdown of CDC6 inhibited while overexpression of CDC6 promoted cancer cell proliferation." (PMID 38685067, 2024). "To confirm the role of OTUD6A in cancer cell proliferation regulation in vivo, we subsequently utilized subcutaneous xenograft mouse models." (PMID 38685067, 2024). "The Cell Counting Kit-8 (CCK8), colony formation and EdU incorporation assays showed that knockdown of OTUD6A inhibited the proliferation of all the cancer cells detected." (PMID 38685067, 2024). "Our results confirmed the synergistic effect of ATR/Chk1 inhibitors and gemcitabine in OTUD6A-overexpressing BCa cells, suggesting the possible beneficial effects of targeting ATR/Chk1 in cancers with high expression of OTUD6A and CDC6." (PMID 38685067, 2024). "According to the qPCR screening, a cancer gene CKS2 was validated as the most induced cell cycle regulator when OTUD6A was overexpressed." (PMID 33669244, 2021). "Conversely, the overexpression of OTUD6A increases Drp1 levels and its protein half‐life and enhances cancer cell growth." (PMID 33070427, 2020). "To assess the biological roles of OTUD6A in cancer, we inhibited the expression of OTUD6A in cells with shRNA." (PMID 33070427, 2020). "We found that missing MDVD domain truly affects the binding of OTUD6A and the cancer cell proliferation." (PMID 33070427, 2020). "Altogether, these results suggest that OTUD6A‐induced cancer cell growth was partly Drp1‐dependent and Drp1 MDVD domain is critical in this signaling pathway." (PMID 33070427, 2020). "OTUD6A can increase the stability and promote the expression of Drp1 protein through ubiquitination, which promotes the onset of Drp1-mediated mitochondrial fission, and enhances the proliferation and colony formation of cancer cells." (PMID 41050073, 2025). "Here, we found that OTUD6A upregulated CDC6 protein level in several types of cancer cells." (PMID 38685067, 2024). "Importantly, ectopic expression of CDC6 effectively reduced the defects in cell proliferation of cancer cells and restored the decreased level of chromatin-bound MCM2 in vitro caused by OTUD6A knockdown." (PMID 38685067, 2024). "Conversely, stably expressed OTUD6A could apparently enhance cancer cell biological behaviors, including proliferation and colony formation." (PMID 33070427, 2020). "Thus, our study implicates the possibility of OTUD6A as a potential cancer therapeutic target." (PMID 33669244, 2021). "Therefore, the present study and the previous reports suggest that OTUD6A could be a feasible therapeutic target in human cancers." (PMID 33669244, 2021). "The results suggest that OTUD6A may serve as a therapeutic target in human cancers." (PMID 33669244, 2021). "In this review, we comprehensively summarize the roles of seven DUBs with OTU structural domains in cancer progression and antiviral immune responses, including OTUD1, OTUD2, OTUD3, OTUD4, OTUD5, OTUD6A, and OTUD6B." (PMID 41050073, 2025). "Similar to the results obtained in OTUD6A-knockdown cells, knockdown of CDC6 increased the sensitivity of cancer cells to anticancer chemotherapeutic drugs and HU." (PMID 38685067, 2024).
cancer (continued). "Consistent with findings in OTUD6A knockdown cancer cells, overexpression of OTUD6A increased the protein level but not the mRNA level of CDC6 in UMUC3 and 786-O cells." (PMID 38685067, 2024). "However, the exogenous expression of the Drp1‐ΔMDVD did not restore the suppression of cancers induced by OTUD6A." (PMID 33070427, 2020). "Overexpression of the C152A mutant of OTUD6A could also impact cell growth but it is slight and not stronger than OTUD6A, suggesting that other signaling pathways independent of Drp1 might be involved in OTUD6A‐mediated cancer cell growth." (PMID 33070427, 2020).
infection (2 papers, 2017 to 2023). The state of being infected such as from the introduction of a foreign agent such as serum, vaccine, antigenic substance or organism. "To investigate the function of OTUD6A in vivo, we established an acute infection model by injecting HSV-1 into mice." (PMID 37632103, 2023). "To explore the role of OTUD6A in vivo, we established an acute infection model by infecting mice with LPS." (PMID 37632103, 2023). "As hypothesized, overexpression of OTUD6A led to significant inhibition of Ifnβ expression following infection with any of these viruses, thus confirming its negative regulatory role in the expression of Ifnβ." (PMID 37632103, 2023). "Six UPS factors were discovered to be essential for infection with the three viruses (DCAF12L, DDB1, FBXL19, OTUD6A, PAN2, and PHC2)." (PMID 29202037, 2017).
bacterial infections (1 paper, 2023). "Our data revealed that OTUD6A can both inhibit innate immunity and promote inflammatory response, highlighting its importance in accelerating the cellular response to deadly virus or bacterial infections." (PMID 37632103, 2023).
infectious disease (1 paper, 2023). A disorder directly resulting from the presence and activity of a microbial, viral, or parasitic agent in humans. "Taken together, our findings suggest that OTUD6A plays a crucial role in the innate immune response and may serve as a potential therapeutic target for infectious disease." (PMID 37632103, 2023).
OTUD6A also shares sentences with these, for which no sentence is quoted: acinar adenocarcinoma (1 paper); allergic asthma (1); cardiac hypertrophy (1); glioblastoma (1); glioma (1); head and neck squamous cell carcinoma (1); heart failure (1); intrahepatic cholangiocarcinoma (1); non-small cell lung carcinoma (1); viral infections (1).